NOX1 (NADPH oxidase 1)
Diseases named in the same sentence as NOX1 in open-access papers (continued):
Sharing a sentence is not in itself a finding about the gene and the disease.
pulmonary fibrosis (5 papers, 2013 to 2024). Chronic progressive interstitial lung disorder characterized by the replacement of the lung tissue by connective tissue, leading to progressive dyspnea, respiratory failure, or right heart failure. "Several lines of pre‐clinical evidence have demonstrated that effects of genetic NOX1/4 deficiency are consistent with those of setanaxib in human lung cells and animal models of lung fibrosis." (PMID 36658776, 2023). "This narrative review critically examines the role of NOX1/4 in liver, kidney and lung fibrosis, alongside the available evidence investigating setanaxib as a therapeutic agent in pre‐clinical models of disease." (PMID 36658776, 2023). "GKT137831, a selective NOX1/4 inhibitor, is currently under clinical trial as a potential therapeutic of idiopathic pulmonary fibrosis (IPF)." (PMID 37134122, 2023). "Activation of NOX enzymes was the major source of ROS production in cells, and NOX1/2/4 were considered to play an essential role in the development of pulmonary fibrosis." (PMID 29849916, 2018). "This narrative review critically discusses the role of NOX1/4‐mediated ROS production in liver, kidney and lung fibrosis, the pre‐clinical evidence in support of setanaxib as a therapeutic agent in the pre‐clinical setting, and the potential clinical translatability of such pre‐clinical evidence." (PMID 36658776, 2023). "However, while there is evidence demonstrating that NOX1/4 play an important role in progressing lung fibrosis, the cell‐type‐related functional differences of NOX1/4 in fibrotic pathologies must be considered." (PMID 36658776, 2023). "NOX1, NOX2, and NOX4 are involved in the initiation of liver fibrosis, while NOX4 mediates idiopathic pulmonary fibrosis." (PMID 39456409, 2024). "Both NOX1 and NOX4 are key players in epithelial cell death, leading to pulmonary fibrosis and acute lung injury." (PMID 23671702, 2013). "Ongoing clinical trials of NOX inhibitors include tests with GKT137839, also known as setanaxib, a preferential direct inhibitor of NOX1 and NOX4, in patients with primary biliary cholangitis and idiopathic pulmonary fibrosis (NCT05014672 and NTC03865927, respectively)." (PMID 39456409, 2024). "ROS derived from NOX1 and NOX4 are key mediators of liver, kidney and lung fibrosis." (PMID 36658776, 2023).
viral infection (5 papers, 2013 to 2022). "Out of seven NADPH oxidase homologs, four are implicated in ROS generation under viral infections: Nox1, Nox2, Nox4, and Duox2, but the primary source of inflammatory cell ROS is the Nox2 oxidase enzyme." (PMID 35281470, 2022). "HkX-31 virus infection of Nox1−/y mice resulted in significantly greater: loss of bodyweight (Day 3); BALF neutrophilia, peri-bronchial, peri-vascular and alveolar inflammation; Nox2-dependent inflammatory cell ROS production and peri-bronchial, epithelial and endothelial oxidative stress." (PMID 23577160, 2013). "Apart from Nox2, also Nox1, Nox 4, and Duox2 might play a role in the ROS formation of viral infections." (PMID 35281470, 2022). "Other genes that are well-known to be upregulated with early viral infection such as ISG15 and interleukin (IL)-1β were also commonly upregulated on day 1 p.i. along with NADPH oxidase 1 (NOX1)." (PMID 31635289, 2019).
asthma (4 papers, 2020 to 2023). "Moreover, NOX1 is an oxidative stress-induced gene that is highly linked to lung inflammation in asthma and COPD disorders." (PMID 32512817, 2020). "But NOX1 had the best ability to differentiate between mild and moderate asthma, with AUC of 0.798 (GSE43696) and 0.826 (GSE63142), respectively." (PMID 36862916, 2023). "Notably, NOX1 was screened from the ferroptosis database and our subsequent machine learning analysis, demonstrating its importance in ferroptosis of asthma airway epithelial cells." (PMID 36862916, 2023). "Furthermore, our results showed an upregulation of NOX1 expression in AEC from children with asthma, which directly correlates with the increased levels of CCL11." (PMID 37860000, 2023). "Although the role of NOX1 in asthma is unknown, NOX1 plays an important role in alveolar cell injury during hyperoxia in knockout mice." (PMID 35796922, 2022).
cervical carcinoma (4 papers, 2018 to 2023). A carcinoma arising from either the exocervical squamous epithelium or the endocervical glandular epithelium. "High expression of NOX1 is reported to be associated with poor prognosis of cervical cancer patients." (PMID 37679792, 2023). "In summary, exosomal NOX1 promotes tumor-associated macrophage M2 polarization-mediated cancer progression through stimulating ROS production in cervical cancer." (PMID 37679792, 2023). "Upregulation of NOX1 may be associated with infiltration of M2-type macrophages in cervical cancer tissues, and NOX1 promotes malignant features of cervical cancer cells by stimulating ROS production." (PMID 37679792, 2023). "Elucidation of whether NOX1-carrying exosomes are involved in the regulation of TAMs may therefore provide valuable insights into the mechanisms associated with progression of cervical cancer." (PMID 37679792, 2023). "Exosomal NOX1 promotes TAM M2 polarization-mediated cancer progression through stimulating ROS production in cervical cancer." (PMID 37679792, 2023). "Our findings clearly suggest that NOX1 promotes malignant features of cervical cancer cells via stimulation of ROS production." (PMID 37679792, 2023). "The collective findings provide a valuable insight into the potential mechanisms by which oncogenic NOX1 promotes cervical cancer progression." (PMID 37679792, 2023). "Exosomal NOX1 enhances progression of cervical cancer and M2 polarization in vivo by stimulating ROS production." (PMID 37679792, 2023). "RT-PCR and IHC analyses confirmed the significant overexpression of NOX1 in cervical cancer compared with adjacent normal tissues." (PMID 37679792, 2023). "Further analysis of NOX1 mRNA levels in nine NSCLC and two cervical cancer cell lines, with known LKB1 mutational status, showed that almost all cell lines bearing LKB1 mutations presented increased NOX1 expression compared with LKB1 wild-type cells." (PMID 29915721, 2018). "We further evaluated the expression patterns of NOX1 in cervical cancer." (PMID 37679792, 2023). "Elucidation of the mechanisms of NOX1-carrying exosomes involved in the regulation of TAMs may provide valuable insights into the progression of cervical cancer." (PMID 37679792, 2023). "NADPH oxidase 1 (NOX1) gene-mediated production of reactive oxygen species (ROS) could induce migration and invasion of cervical cancer cells." (PMID 37679792, 2023). "Furthermore, overexpression of NOX1 promoted HeLa cell growth in vivo, supporting its carcinogenic role in cervical cancer." (PMID 37679792, 2023). "In this study, we investigated the expression patterns of NOX1 in cervical cancer." (PMID 37679792, 2023). "Our collective findings suggest that NOX1-carrying exosomes promote the malignant features of cervical cancer by regulating TAMs via ROS production, providing a theoretical basis and novel targets for effective clinical treatment of cervical cancer." (PMID 37679792, 2023). "However, expression of NOX1 was significantly higher in cancer tissues relative to the corresponding adjacent normal counterparts, including cervical cancer." (PMID 37679792, 2023). "Cell experiment and animal tumor formation experiment were used to evaluate whether exosomal NOX1 stimulating ROS production to promote M2 polarization of TAM in cervical cancer." (PMID 37679792, 2023). "However, expression patterns of the NOX1 gene in cervical cancer and adjacent tissues and its tumor-promoting mechanisms remain to be established." (PMID 37679792, 2023). "RT-PCR and IHC results consistently showed elevated expression of NOX1 in cervical cancer tissues compared with adjacent normal tissues, prompting further investigation of the potential functions and mechanisms of action of NOX1 in cervical cancer." (PMID 37679792, 2023).
cervical carcinoma (continued). "Although marked heterogeneity in the expression levels of NOX1 among LKB1-deficient lung and cervical cancer cell lines does not allow us to generalize these findings, our results hint at NOX1 as a candidate mediator of angiogenesis in a subset of LKB1-deficient tumors." (PMID 29915721, 2018). "In fact, real-time PCR experiments showed marked differences in the relative expression levels of NOX1 among the NSCLC and cervical cancer cell lines analyzed." (PMID 29915721, 2018). "In particular, NOX1 was highly expressed in cervical cancer tissues relative to the non-tumor counterparts with a mutational frequency of 2.1%." (PMID 37679792, 2023). "Based on QUANTISEQ analysis, a significant positive correlation between NOX1 expression and M2-type, but not M1-type macrophage infiltration was observed in cervical cancer tissues." (PMID 37679792, 2023).
Cognitive impairment (4 papers, 2016 to 2022). Abnormal cognition is characterized by deficits in thinking, reasoning, or remembering. "In doxorubicin (DOX)-impaired rats, galangin significantly mitigates cognitive impairment and neurotoxicity via the NOX-1/Nrf-2/HMGB1/TLR4 and TNF-α/MAPKs/RIPK/MLKL/BDNF pathways." (PMID 36015161, 2022). "There was a high correlation between cognitive impairment and A11 oligomer production, NOX4, and Aβ expression, except for NOX1 expression." (PMID 30736297, 2019).
diabetic retinopathy (4 papers, 2019 to 2026). "Inhibition of Nox1/4 in bovine endothelial cells reduces the high glucose induced oxidative stress, angiogenic and inflammatory markers, indicated the potential of Nox1 and Nox4 inhibition in reducing the vision damage associated with diabetic retinopathy." (PMID 34571964, 2021). "NOX1 contributes to diabetic retinopathy, and NOX2 function has been demonstrated to be crucial in insulin resistance." (PMID 35740948, 2022).
ischemic stroke (4 papers, 2010 to 2022). A stroke disorder caused by obstruction of blood flow to the brain, due to thrombotic (local blood clot formation) or embolic (due to a blood clot or other material traveling from another site) event. "In an interesting study using NOX1, NOX2 and NOX4 deficient mice as well as the specific NOX Inhibitor VAS2870, the pathophysiological role of the different NOX isoforms in ischemic stroke has now been assessed in terms of infarct development and blood-brain-barrier damage." (PMID 20356357, 2010). "Upregulation of Nox1 is widely observed during recovery from ischemic stroke, suggesting that there could be mechanistic parallels between the impact of acute intrapartum ischemia-hypoxemia on the fetal brain and ischemic stroke." (PMID 33963277, 2021). "An essential finding has been shown that the oxidative markers including inducible nitric oxide synthase (iNOS), NADPH oxidase-1 (NOX-1), and NOX-2, are notably elevated in the ischemic stroke mice model." (PMID 36124014, 2022).
kidney damage (4 papers, 2011 to 2022). "ML171 reduced H2O2 in the IRI mouse, and the effect was manifested as a subsequent increase in SOD2 and GPX in MDCK cells, suggesting the prevention of kidney damage with oxidative stress by selective NOX1 inhibition." (PMID 32967113, 2020).
liver diseases (4 papers, 2020 to 2025). "A recent study reported that NOX1-derived ROS played a critical role in liver disease." (PMID 36829609, 2023). "But it is not clear how and what exact role NOX1 mRNA in exosomes play in the development of the liver diseases caused by HBV." (PMID 32001731, 2020). "In a study conducted on rats, inhibition of NOX1/4 using GKT137831 significantly reduced portal pressure, improved hyperdynamic circulation, mesenteric angiogenesis, and arterial hyporesponsiveness in rats with portal hypertension." (PMID 39997697, 2025).
lung disease (4 papers, 2017 to 2024). "NOX-1 is expressed in several tissues including the lung where it seems to be up-regulated in pathological conditions in lung disease." (PMID 39014440, 2024). "However, there are still knowledge gaps concerning the precise role of NOX1/4 in fibrotic pathologies that underlie liver, kidney and lung disease, and the selective inhibitory action of setanaxib has not been fully elucidated." (PMID 36658776, 2023).
osteoporosis (4 papers, 2016 to 2021). A condition of reduced bone mass, with decreased cortical thickness and a decrease in the number and size of the trabeculae of cancellous bone (but normal chemical composition), resulting in increased fracture incidence. "In a previous study, the specific NOX1/2/4 inhibitor Ewha-18278 was confirmed as a possible treatment for osteoporosis both in vitro and in vivo." (PMID 31533299, 2019). "Among seven NOX members, NOX1, 2, and 4 play crucial roles in osteoporosis." (PMID 31533299, 2019). "Based on the notion that the differentiation of OCs is mediated by Nox1/2/4-dependent ROS generation, we have performed a high throughput enzyme inhibitor screening assay to identify chemical compounds having Nox1/2/4 inhibitory activity for the development of an anti-osteoporosis agent." (PMID 26975635, 2016). "Our results demonstrate the novel action mechanism of E2 in OCs to impair cytoskeletal reorganization in a non-genomic way, suggesting that SHP2 or NOX1 could be a potential therapeutic target for osteoporosis upon loss of ovarian function." (PMID 33920630, 2021). "Thus, Nox1/2/4 inhibitor is likely to be a more effective agent for the treatment of osteoporosis." (PMID 26975635, 2016). "In the beginning stage, we developed a novel lead compound, #1, for selective inhibition of NOX1 and NOX4 in the treatment of osteoporosis." (PMID 31533299, 2019). "The novel pyrazole derivative Ewha-18278 was developed to selectively inhibit NOX1, NOX2, and NOX4 to treat osteoporosis." (PMID 31533299, 2019).
preeclampsia (4 papers, 2021 to 2024). Preeclampsia is a hypertensive disorder of pregnancy that is characterized by new-onset hypertension with proteinuria presenting after 20 weeks of gestation, and depending on mild or severe forms may initially present with severe headache, visual disturbances, and hyperreflexia. "However, the overexpression of NOX1 increases oxidative stress and is associated with preeclampsia." (PMID 34360662, 2021).
thyroid cancer (4 papers, 2015 to 2024). "In addition, NOX1 was shown to promote the self-renewal activity of CD133+ thyroid cancer cells through activation of AKT signaling." (PMID 33081375, 2020). "NOX1, NOX3, and NOX5 expression suggested minor changes in thyroid cancers, whereas the expression of NOX2 and NOX4 showed increased mRNA synthesis in papillary thyroid and anaplastic thyroid cancers." (PMID 26664298, 2015). "Thus, the Oncomine Giordano and He database results showing thyroid cancer-related redox gene expression suggest that NOX1, NOX3, and NOX5 mRNA levels do not markedly change in tumorigenesis, whereas NOX2 and NOX4 expression showed increased levels correlating with the degree of transformation." (PMID 29478325, 2019).
urothelial carcinoma (4 papers, 2011 to 2025). A malignant neoplasm derived from the transitional epithelium of the urinary tract (urinary bladder, ureter, urethra, or renal pelvis). "Silencing of ALKBH8 induces apoptosis and downregulation of NADPH oxidase 1 (Nox1) dependent reactive oxygen species, whereas invivo it significantly suppresses invasion, angiogenesis, and growth of human urothelial carcinoma cells." (PMID 39723662, 2025). "Previously, we showed that a novel isoform of the DNA repair enzyme ALKBH, ALKBH-8, contributes to progression of urothelial carcinoma cells via NOX1-ROS signal-mediated resistance to apoptosis induction." (PMID 22032647, 2011). "At the beginning of the experiment, the expression of NOX family members, apart from NOX1, was examined in the human urothelial carcinoma cell lines T24, UMUC6, and KK47." (PMID 22032647, 2011). "NOX4 is expressed at very low levels in human normal urothelium whereas NOX1, NOX2, and NOX4 are overexpressed in urothelial carcinoma patients." (PMID 36670953, 2022). "Therefore, in addition to NOX1, NOX4 is required for the maintenance of intracellular ROS in urothelial carcinoma cells." (PMID 22032647, 2011). "Recently, we identified generation of intracellular hydrogen peroxide by NOX1 as a major downstream signal for a novel human AlkB homologue, ALKBH-8, that contributes to cell survival by enhancing resistance to apoptosis in human urothelial carcinoma cells, both in vitro and in vivo." (PMID 22032647, 2011).
acute kidney injury (3 papers, 2020 to 2023). Sudden and sustained deterioration of the kidney function characterized by decreased glomerular filtration rate, increased serum creatinine or oliguria. "Nevertheless, this is the first study to investigate the renoprotective effect of NOX1 inhibition on the kidneys and kidney tubule cells, which makes it a candidate for treatment of acute kidney injury." (PMID 32967113, 2020). "In addition, we recently reported that XO inhibition attenuated contrast-induced acute kidney injury by modulating oxidative stress through the inhibition of NOX1 and NOX2, while simultaneously enhancing dephosphorylation of FoxO1 and FoxO3a." (PMID 36835220, 2023). "NOX1 inhibition by ML171 and siRNA against NOX1 reduced the oxidative stress-induced apoptosis in MDCK cells, indicating NOX1 selective inhibition’s potential as a therapeutic target for acute kidney injury associated with ROS generation and subsequent apoptosis." (PMID 32967113, 2020).
Cirrhosis (3 papers, 2015 to 2025). A chronic disorder of the liver in which liver tissue becomes scarred and is partially replaced by regenerative nodules and fibrotic tissue resulting in loss of liver function. "The deficiency of NOX1 or NOX4 prevents liver inflammation and fibrosis in mice and NOX1 and NOX4 protein levels are increased in human livers with cirrhosis compared with normal controls." (PMID 34571961, 2021). "Finally, NOX1 and NOX4 protein levels were increased in human livers with cirrhosis compared with normal controls." (PMID 26222337, 2015). "Furthermore, NOX1 and NOX4 are increased in patients with cirrhosis." (PMID 26222337, 2015).
fibrosis (3 papers, 2015 to 2019). the formation of excess fibrous connective tissue in an organ or tissue in a reparative or reactive process. "In the lung, it has been shown that some pro-oxidant enzymes such as NADPH oxidase-1 (NOX1), NOX2, NOX4, as well as Duox1 and Duox2 are involved in oxidative stress and development of fibrosis." (PMID 31366142, 2019).